PRMT5 (protein arginine methyltransferase 5)
Diseases named in the same sentence as PRMT5 in open-access papers (continued):
Sharing a sentence is not in itself a finding about the gene and the disease.
cancer (continued). "Firstly, they provide a strong basis for targeting PRMT5, which not only directly damages the functions of cancer cells but also enhances antitumor immunity by enhancing the infiltration of CD8+ T cells into the tumor microenvironment." (PMID 41463372, 2025). "The cancer-associated mutations evaluated in this study destabilize MEP50, likely impacting methylosome complex integrity and PRMT5 enzymatic activity, thereby disrupting hormone signaling and DNA repair pathways." (PMID 40919714, 2025). "PRMT5, a type II methyltransferase catalyzing symmetric dimethylation of arginine residues, has emerged as a promising therapeutic target in various cancers." (PMID 41463372, 2025). "Inhibition of themethyltransferase enzyme PRMT5 by MTAaccumulationis a vulnerability of MTAP-deleted cancers." (PMID 40102181, 2025). "MAT2A inhibitors were developed later than PRMT5 inhibitors and only two molecules are in Phase II clinical trials concerning cancer patients with MTAP deletion." (PMID 41465382, 2025). "PRMT5 is a histone methyltransferase upregulated in various cancer types, but its role in regulating alternative splicing events via histone methylation has not been explored." (PMID 41150697, 2025). "The JAK1/TLR3/PRMT5/c-Myc axis provides potential targets for cancer and reasonable evidence for predicting chemotherapeutic efficacy and patients' prognosis." (PMID 40675966, 2025). "In this way, it is anticipated that PRMT5 inhibition will improve the way that immunological checkpoint treatment reacts to unresponsive cancers." (PMID 39781264, 2025). "Reducing methionine concentrations in the culture medium sensitized cancer cells to Prmt5 inhibition supporting a mechanistic link between methionine dependence of cancer and splicing." (PMID 39862967, 2025). "Inhibition of PRMT5 can affect various cellular processes and has been extensively studied for its potential in cancer therapy." (PMID 41463372, 2025). "PRMT5 is currently being tested as a potential therapeutic target in several cancer types, and PRMT5 inhibition is currently in clinical trials." (PMID 40864819, 2025). "PRMT5 has been identified as a synthetic lethal target in cancers with a homozygous deletion of the MTAP gene, which is commonly co-deleted with the tumor suppressor gene CDKN2A." (PMID 40362535, 2025). "Here, inhibition of PRMT5 using EPZ015666 has a more prominent anti-cancer effect in PCa samples with increasing aggressiveness." (PMID 40968252, 2025). "The expression of PRMT5, a critical epigenetic regulator of PTMs, is elevated in several cancers, particularly in CRC, and this increased expression is linked to a low patient survival rate." (PMID 39781264, 2025). "Combined with our new findings, this suggests that PRMT5 plays a crucial role in suppressing ferroptosis in cancer cells and is expected to serve as a potential critical target for cancer therapy." (PMID 40756764, 2025). "Our results demonstrate a link between the cancer-specific nutritional requirement for exogenous methionine and modulation of spliceosome activity through inefficient Prmt5-mediated methylation of splicing factors such as SmD1." (PMID 39862967, 2025). "Another novel PRMT5 inhibitor, JNJ-64,619,178, exhibits sustained PRMT5 inhibition and significant antiproliferative action in a variety of cancer cell lines." (PMID 39885614, 2025). "PRMT5 is required for survival of MYC-driven cancer cells, and has been extensively studied as a potential cancer therapeutic target." (PMID 40326560, 2025). "Another study aimed to evaluate the effect of curcumin on the expression of PRMT5 and its cofactor MEP50—key epigenetic regulators implicated in cancer progression." (PMID 40880749, 2025). "PRMT5 is a type II protein arginine methyltransferase that regulates several tumorigenic events in many cancer types." (PMID 41150697, 2025). "PRMTs, specifically PRMT5, are generally upregulated in several cancers, suggesting their oncogenic tumor-promoting function." (PMID 40091834, 2025).
cancer (continued). "BMS-986504 (MTRX1719) is the second generation of MTA-cooperative PRMT5 inhibitors designed to preferentially bind to the PRMT5-MTA complex which accumulates in cancer cells with MTAP deletion." (PMID 41465382, 2025). "Previous large-scale functional screens identified PRMT5 as a synthetic lethal target in MTAP-deleted cancer cells." (PMID 41246302, 2025). "This preclinical and early clinical data support a synthetic lethal strategy targeting PRMT5 in MTAP-deleted cancers." (PMID 39885614, 2025). "More critically, specific genetic abnormalities, such as MTAP codeletion with the CDNK2A tumor suppressor gene, observed in approximately 15% of cancers, create an additional vulnerability to PRMT5 depletion." (PMID 40091834, 2025). "Several cancer-associated mutations have been identified in PRMT1 and PRMT5, particularly within or near the SAM binding site and dimerization domains, which are critical for enzymatic function." (PMID 40791817, 2025). "PRMT5 is key in the initiation and progression of cancer, with its regulatory roles and functions being critical to cancer development." (PMID 39964832, 2025). "As such, genetic or siRNA-mediated depletion of PRMT1 or PRMT5 levels result in decreased cancer cell proliferation and co-operate with DNA damaging chemotherapies to reduce cell viability." (PMID 40823091, 2025). "To this end, we initially studied PRMT5 expression in more than 1,000 cancer cells in the Cancer Cell Line Encyclopedia (CCLE) database." (PMID 40091834, 2025). "Consistent with findings in other cancer cell lines, we observed that the PRMT5 inhibitor JNJ-64619178 (onametostat) effectively reduced MKL-1 cell viability at sub-nanomolar doses after 8 and 11 d of treatment." (PMID 40846633, 2025). "Consistent with its role in preventing exon skipping in MYC-driven cancers, PRMT5 likely promotes SRSF1 recruitment to Tip60 pre-mRNA to support splicing of full-length, catalytically active Tip60." (PMID 40846633, 2025). "Protein arginine methyl transferase 5 (PRMT5) plays a global role in cell physiology and is an established therapeutic target in cancer." (PMID 41339334, 2025). "Protein arginine methyltransferase 5 (PRMT5) inhibitors significantly downregulate the expression levels of various DDR‐related genes in cancer cells, thereby increasing the sensitivity of cancer cells to chemotherapeutic agents." (PMID 41473689, 2025). "We therefore explored The Cancer Genome Atlas (TCGA) data to study cancer type–specific expression patterns in PRMT5." (PMID 40091834, 2025). "The distribution of PRMT5 expression levels indicates that most cancer types are characterized by normal PRMT5 expression levels." (PMID 40735501, 2025). "Immune checkpoint inhibitors (ICIs) in the treatment of MTAP-null cancers have garnered interest in the research field due to the synergistic effect of PRMT5 inhibition with anti-programmed cell death protein (PD1) drugs." (PMID 41439984, 2025). "We verified the interaction between TLR3 and PRMT5 in the nucleus of Panc1 and A549 cancer cells upon chemotherapeutic stress by immunoprecipitation and immunofluorescence." (PMID 40675966, 2025). "The fact that combinatorial PRMT5 inhibition rendered these cells substantially more sensitive to chemotherapy indicates that cancer cells require even higher levels of PMRT5 to survive chemotherapy and transition to a chemo-resistant state." (PMID 40091834, 2025). "In another example, the MTA-cooperative PRMT5 inhibitor, MRTX1719, demonstrates significant inhibitory effects on cancer cells with MTAP deletions by selectively binding to the PRMT5/MTA complex." (PMID 39826691, 2025). "Protein Arginine Methyltransferase 5 (PRMT5), a key epigenetic regulator, has been implicated in modulating the ERK1/2 and PI3K pathways in cancer." (PMID 41226455, 2025). "Loss of MTAP leads to accumulation of MTA, which competitively binds to the active domain of the PRMT5 enzyme, thereby increasing cancer cell dependence on PRMT5." (PMID 41439984, 2025).
cancer (continued). "The nuclear TLR3 is found to be able to recruit the arginine methyltransferase PRMT5 to promote symmetrical dimethylation and multimerization of c-Myc in cancer cells." (PMID 40675966, 2025). "It has been demonstrated that MTAP deficiency, leading to MTA accumulation, offers a therapeutic window by creating a hypomorphic PRMT5 state that selectively sensitizes cancer cells to PRMT5 inhibition." (PMID 40603833, 2025). "PRMT5 is an established anti-cancer target for which various classes of inhibitors have been developed." (PMID 41339334, 2025). "A clinical phase 1 trial has shown significant size reduction of MTAP‐deleted cancers after treatment with the PRMT5 inhibitor MRTX1719." (PMID 39668577, 2025). "Protein arginine N-methyltransferase 5 (PRMT5) has been identified as a potential therapeutic target for various cancer types." (PMID 38666828, 2024). "It has been shownthat PRMT5 inhibition by small molecules canselectively kill cancer cells with homozygous deletion of the MTAP gene if the inhibitors can leverage the consequenceof MTAP deletion, namely, accumulation of the MTAPsubstrate MTA." (PMID 38595098, 2024). "A variety of PRMT5 inhibitors have been developed and are currently being examined in clinical trials for cancer therapy." (PMID 38503742, 2024). "In this study, we analyzed SCC patient data from The Cancer Genome Atlas (TCGA) and the Cancer Dependency Map (DepMap) to investigate the relationship between PRMT5 and SCC proliferation." (PMID 39594744, 2024). "PRMT5 dimethylated proteins participate in a number of regulatory pathways that can contribute to tumor development and progression implicating PRMT5 as a target for cancer therapy." (PMID 39068290, 2024). "This is especially relevant as recent studies have suggested that PRMT5 inhibitors can increase the sensitivity of cancer cells to chemotherapeutics, even in resistant populations." (PMID 38049564, 2024). "Treatment with CMP5 selectively reduces the viability of tumor cells, suggesting that PRMT5 is an ideal therapeutic target against cancer." (PMID 38612768, 2024). "The aggarwal group ascertained that cyclin D1T286A, CDK4, MEP50 and PRMT5 coprecipitate in B cells and human cancer cells." (PMID 39255317, 2024). "Genetic knockdown screening libraries revealed that in the 15% of cancers with MTAP loss, enhanced dependence is conferred on methylthioadenosine transferase 2 alpha (MAT2a, EC:2.5.1.6) and protein arginine methyltransferase 5 (PRMT5, EC:2.1.1.320)." (PMID 38000655, 2024). "Our findings highlight a unique role for PRMT5 in regulating ΔNp63α in SCC, distinct from the established PRMT5/TAp63 interaction in other cancers, offering new insights into SCC biology." (PMID 39594744, 2024). "Isolated studies have demonstrated that the knockout of PRMT5 in LC cells results in a decreased proliferation rate of cancer cells by disrupting the activity of the Smad7/STAT3 signaling axis." (PMID 39678513, 2024). "In particular, it is overexpressed in many cancers and elevated PRMT5 expression often correlates with poor prognosis." (PMID 38372724, 2024). "Therapies targeting of MAT2A, RIOK1, or other PRMT5 co‐complex members selectively affect MTAP‐deleted cancers while sparing MTAP‐expressing normal tissues, which address the unmet clinical need of human cancers with the deletion of the MTAP locus." (PMID 39711357, 2024). "MAT2A was found as a synthetic lethal target in methylthioadenosine phosphorylase (MTAP)‐deficient cancer cells, and the mechanism involves SAM‐utilizing protein arginine methyltransferase 5 (PRMT5)." (PMID 39309689, 2024).
cancer (continued). "STAT3 expression was induced by v-SRC, a typical oncogenic signalling molecule known to activate STAT347, suggesting that STAT3 is involved in the regulation of PRMT5 expression in cancer cells." (PMID 38760429, 2024). "In conclusion, while we describe a role of PRMT5 activity in the context of RS, these findings also have implications for the use of PRMT5 inhibitors concomitantly with RS inducing cancer treatments." (PMID 38838142, 2024). "The combination of MTDIA with an MTA-cooperative PRMT5 inhibitor is found to be more toxic against the cancers than the host." (PMID 38000655, 2024). "PRMT5 inhibitors have been developed and tested in clinical trials for cancer treatment (ClinicalTrials.gov NCT03573310 and NCT05094336, among others)." (PMID 39146021, 2024). "We discovered a potent and specific allosteric MAT2A inhibitor SCR‐7952, with promising inhibition on the growth of MTAP‐deleted cancers, via the regulation of PRMT5 activity and its downstream." (PMID 39309689, 2024). "The protein arginine N-methyltransferase 5 (PRMT5) has been identified as a promising therapeutic target in various cancers." (PMID 38666828, 2024). "In conclusion, the data presented in this study strongly suggested a positive correlation between PRMT5 expression and various pro-cancer pathways, notably the HIF1α pathway in HCC." (PMID 38666828, 2024). "It has to be mentioned that PRMT5 is considered as one of the promising targets in cancer due to its effects on the cell proliferation, invasion and migration." (PMID 38730267, 2024). "In BC cells, PRMT5 is recruited to the Forkhead Box P1 (FOXP1) promoter, a winged helix/forkhead transcription factor associated with cancer stem cell function and facilitates H3R2 methylation." (PMID 39201539, 2024). "The therapeutic use of PRMT5-specific inhibitors is under development, and a variety of ongoing cancer clinical trials are investigating their pharmacokinetics as well as their beneficial and adverse effects." (PMID 38503742, 2024). "In this study, we found that STAT3 can induce PRMT5 expression, suggesting that cancer-promoting functions of PRMT5 other than STAT3 activation are involved in the oncogenic function of STAT3." (PMID 38760429, 2024). "According to literature, inhibition of PRMT5 has been termed an efficient strategy in cancers featuring deletion of the methylthioadenosine phosphorylase gene (MTAP), as such cancers rely on PRMT5 for survival." (PMID 38383756, 2024). "A key reason for the enhanced PRMT5 expression seen in cancers is the ability of PRMT5 to facilitate cell cycle progression." (PMID 39594744, 2024). "As such, cancers harboring MTAP deletion are more sensitive to additional PRMT5 inhibition than normal cells." (PMID 39337530, 2024). "What's more, MTAP loss results in the accumulation of methylthioadenosine (MTA), which inhibits protein arginine methyltransferase 5 (PRMT5) activity and leads to reduced basal PRMT5 methylation in MTAP‐deleted cancers." (PMID 39711357, 2024). "SCR‐7952 selectively suppressed MTAP‐deleted cancer cell proliferation in vitro and tumor growth in vivo, via regulation of PRMT5 activity and its downstream splicing perturbations." (PMID 39309689, 2024). "SCR‐7952 selectively inhibited the growth of MTAP‐deleted cancers, via the regulation of PRMT5 activity." (PMID 39309689, 2024). "PRMT5, a type II protein arginine methyltransferase, is upregulated in numerous cancers, including TNBC, and plays a critical role, marked it as an attractive therapeutic target." (PMID 39614393, 2024). "This upregulation of PRMT5 promotes cancer progression and metastasis by modulating downstream targets." (PMID 39255317, 2024). "More recently, the PRMT5-MTA complex emerged as a promising drug target for treating MTAP-deleted cancers." (PMID 39201539, 2024). "SDMA posttranslational modification by PRMT5 regulates diverse cellular processes with direct implications for cancer initiation and development." (PMID 38838142, 2024).
cancer (continued). "Given the involvement of exosomes in intercellular communication and cancer metastasis, the impact of PRMT5 on cell-to-cell communication via transfer of exosomes needs to be explored." (PMID 38612768, 2024). "PRMT5 has been reported to impact the anti-tumor function of PD-L1 by regulating its expression, thereby promoting cancer progression." (PMID 39366935, 2024). "Protein arginine methyltransferase 5 (PRMT5) is a critical oncogenic factor in various cancers, and its inhibition has shown promise in suppressing tumor growth." (PMID 39594744, 2024). "The effect of PRMT5 inhibition on blocking the G1-to-S transition in RB1-deleted cells suggests a potential approach to suppress cancer cell proliferation." (PMID 38480701, 2024). "In contrast, immune inhibitory genes in cancer cells, e.g., ENPP1, CTNNB1, PRMT5, were depleted after lymphocyte-cancer co-culture." (PMID 38678024, 2024). "There is also evidence suggesting that PRMT5 plays a role in promoting cancer cell growth and proliferation." (PMID 38666828, 2024). "Several PRMT inhibitors have been discovered and investigated in clinical trials, especially PRMT5 inhibitors, as PRMT5 plays an essential role in cancer stem cell survival, mRNA splicing, and DNA repair processes." (PMID 39309689, 2024). "This discovery not only provides a solid theoretical foundation and experimental evidence for the development of PROTAC drugs targeting PRMT5 and similar proteins but also broadens new avenues for cancer treatment." (PMID 39614393, 2024). "PRMT5-mediated arginine methylation of histone proteins can repress expression of epithelial junctional genes, thereby promoting cancer cell invasion." (PMID 38612768, 2024). "Loss of MTAP leads to the accumulation of MTA and renders these cancer cells vulnerable to inhibition of protein arginine methyltransferase 5 (PRMT5)." (PMID 38698089, 2024). "Extensive clinical and preclinical research has indicated that PRMT5 exhibits ectopic expression across various cancer types and is negatively correlated with favorable prognostic outcomes." (PMID 39678513, 2024). "GlaxoSmithKline (GSK) has found that both the PRMT1 inhibitor GSK3368712 (GSK712) and the PRMT5 inhibitor GSK3326593 (GSK593) have anti-tumor effects in a variety of cancer cell lines, with the exception of HNSCC." (PMID 38709899, 2024). "PRMT5 is essential for the proliferation and survival of cancer cells, and overexpression of PRMT5 is found in various types of human cancers." (PMID 38503742, 2024). "PRMT inhibitors, particularly those targeting PRMT1 and PRMT5 due to their well-documented role in cancer progression, are being investigated as therapies for hematological malignancies and solid tumors and have progressed to clinical trials." (PMID 39201539, 2024). "Harnessing homeostatic metabolism to shift metabolite ratios in favor of MTA pool size alters PRMT5 activity and presents a useful approach to the design of cancer therapeutics." (PMID 38000655, 2024). "Note that the cytotoxicity of PRMT inhibitors, especially inhibitors for PRMT5, are shown to be more specific towards cancer cells because of PRMT overexpression in cancer tissues and the reliance of tumor cells on PRMT activity." (PMID 38612768, 2024). "PRMT5 plays critical roles in tumorigenesis and is therefore a therapeutic target that is actively pursued for cancer treatment." (PMID 38372724, 2024). "Our findings also show that PRMT5 directly adds a dimethyl group to FXR1 arginine residues in cancer cells." (PMID 38709899, 2024). "Combining PRMT5 inhibitors with existing chemotherapeutics has proven beneficial in different cancer types." (PMID 39201539, 2024). "Various PRMT5 inhibitors with different functions have undergone clinical trials for the treatment of advanced cancer or recurrent solid tumors." (PMID 38136401, 2023). "Cytoplasmic and nuclear localization of PRMT5 has also been confirmed in various preclinical mouse models and primary human cancer tissues." (PMID 38136401, 2023).